RNY4P18 (RNY4 pseudogene 18)
Gene: Miscellaneous RNA gene on chromosome 9 (111,097,325 to 111,097,413, reverse strand). Ensembl gene ENSG00000212409.
Homologues: Orthologues: chimpanzee Y_RNA (99% identical). Paralogues in human: RNY4 (94% identical), RNY4P7 (92% identical), RNY4P10 (91% identical), RNY4P24 (91% identical), RNY4P6 (91% identical), Y_RNA (91% identical), RNY4P25 (90% identical), Y_RNA (90% identical), RNY4P13 (89% identical), RNY4P14 (89% identical), RNY4P3 (89% identical), RNY4P34 (89% identical), and 89 more.